WFDC3 (WAP four-disulfide core domain 3)
Synonyms: WAP14; dJ447F3.3
Tractability: Antibody: UniProt places it where antibodies can reach, with high confidence; UniProt predicts a signal peptide or a membrane-spanning region; its Gene Ontology location is reachable by antibodies, with medium confidence.
Gene: Protein-coding gene on chromosome 20 (45,747,944 to 45,791,932, reverse strand). Ensembl gene ENSG00000124116.
Subcellular location: Secreted
Gene Ontology:
Molecular function: protein binding; serine-type endopeptidase inhibitor activity; peptidase inhibitor activity
Biological process: antibacterial humoral response; innate immune response
Cellular component: extracellular region
Genetic constraint (gnomAD): Loss-of-function variants: 14 observed, 23.62 expected, observed/expected ratio (o/e) 0.59, 90% interval 0.39 to 0.93. The upper end of that interval is the gene's LOEUF score, 0.93, which puts it in group 3 of 6, group 1 being the genes least tolerant of losing a copy. Missense variants: 237 observed, 266.45 expected, observed/expected ratio (o/e) 0.89, 90% interval 0.8 to 0.99. Synonymous variants: 92 observed, 99.9 expected, observed/expected ratio (o/e) 0.92, 90% interval 0.78 to 1.1.
Homologues: Orthologues: chimpanzee WFDC3 (99% identical), dog WFDC3 (74% identical), guinea pig WFDC3 (68% identical), rat Wfdc3 (41% identical), mouse Wfdc3 (38% identical), Drosophila melanogaster CG5639 (34% identical), Caenorhabditis elegans C08G9.2 (23% identical). Paralogues in human: SLPI (19% identical), WFDC5 (19% identical), WFDC12 (12% identical), PI3 (10% identical), WFDC10A (9% identical), WFDC10B (9% identical), WFDC13 (8% identical), WFDC9 (8% identical), WFDC11 (6% identical).
Diseases named in the same sentence as WFDC3 in open-access papers:
WFDC3 is named in the same sentence as 9 diseases in open-access papers, as found by Europe PMC text mining. Sharing a sentence is not in itself a finding about the gene and the disease. The quoted sentences say what the papers report.
colorectal cancer (2 papers, 2023 to 2024). A primary or metastatic malignant neoplasm that affects the colon or rectum. "Wfdc3 encodes a member of the WAP-type four-disulfide core (WFDC) domain family, which functions as a protease inhibitor, promoting the ERβ-mediated transcriptional repression of TGFBR1 in colorectal cancer, thus showing a link between WFDC3 and oestrogen receptor." (PMID 39518930, 2024).
asthenospermia (1 paper, 2017). "Wfdc3 was the predicted target gene for hsa-miR-487a, which has been detected in the microRNA expression profile of the sperm of patients with asthenospermia." (PMID 28761781, 2017).
breast carcinoma (1 paper, 2024). "Applying label-free proteomic quantitation method and statistical analysis, several differentially expressed proteins (DEPs) were identified in the serum of breast cancer patients compared to controls, including SBSN, ANG, PCOLCE, and WFDC3 (upregulated), and PFN1, FLNA, and DSG2 (downregulated)." (PMID 39990193, 2024).
male infertility (1 paper, 2017). The inability of the male to effect fertilization of an ovum after a specified period of unprotected intercourse. "However, the role of Wfdc3 in the reproductive process has not been extensively studied, and the association of mutations in the WFDC protease inhibitor gene with male infertility need to further studied." (PMID 28761781, 2017).
pancreatic cancer (1 paper, 2025). "Elevated WFDC3 protein expression in pancreatic cancer cells was confirmed via Western blot analysis." (PMID 40350979, 2025). "Building on previous research and the bioinformatic findings presented above, we hypothesized that WFDC3 functions as a dispensable regulator within the molecular modulation network of pancreatic cancer—a notion further substantiated by in vitro experiments." (PMID 40350979, 2025). "Collectively, these findings indicate that WFDC3 acts as a potent immunosuppressive factor in pancreatic cancer, impairing T cell cytotoxicity through both direct suppression of cytotoxic effector expression and reduced susceptibility to T cell-mediated cell killing." (PMID 40350979, 2025).
pancreatic tumor (1 paper, 2025). "Notably, T helper 2 cells (Th2) were paradoxically elevated in WFDC3-high tumors (P < 0.001), emphasizing the multifaceted immunoregulatory role of WFDC3 in the pancreatic tumor microenvironment." (PMID 40350979, 2025).
cancer (2 papers, 2016 to 2025). A tumor composed of atypical neoplastic, often pleomorphic cells that invade other tissues. "Investigating the interaction between cancer cells with upregulated WFDC3 and other cellular components of the tumor immune microenvironment may yield novel insights into therapeutic strategies targeting WFDC3-mediated immune regulation." (PMID 40350979, 2025). "Besides cancer-related genes, three genes ARL14, CELSR3, and WFDC3 are also observed in our list." (PMID 27610367, 2016).
tumor (2 papers, 2023 to 2025). "Notably, our study is the first to demonstrate that WFDC3 knockdown markedly suppresses tumor cell invasion and migration while enhancing susceptibility to immune-mediated cytotoxicity." (PMID 40350979, 2025). "Subsequent ESTIMATE analysis demonstrated that high WFDC3 expression correlated with significantly lower ImmuneScore, StromaScore, and ESTIMATEScore, indicating reduced immune cell infiltration in the tumor stroma and impaired antitumor immune responses." (PMID 40350979, 2025). "Additional scRNA-seq analysis from our unpublished independent dataset further examined the cellular distribution and potential role of WFDC3 in tumor progression." (PMID 40350979, 2025). "Previous research from our group identified a tumor-suppressive role of WFDC3 in inhibiting estrogen-dependent metastasis via activation of the ERβ/TGFBR1 pathway." (PMID 40350979, 2025). "ESTIMATE-based computational analysis revealed significant differences in tumor microenvironment parameters between high and low WFDC3 expression groups." (PMID 40350979, 2025). "In the present study, WFDC3 was found to be significantly upregulated in PAAD and associated with poor prognosis—a finding that contrasts with previous reports of its tumor-suppressive role in CRC." (PMID 40350979, 2025). "Our discoveries identified WFDC3 as a tumor suppressor that facilitates estrogen-induced inhibition of metastasis through the ERβ/TGFBR1 signaling axis." (PMID 37443102, 2023). "The enriched pathways align with prior observations linking WFDC3 to tumor progression and survival, suggesting it may influence PAAD development through coordinated regulation of cell motility and immune dynamics." (PMID 40350979, 2025). "Substantial evidence links dynamic cytoskeletal remodeling to tumor metastasis, suggesting that WFDC3 may contribute to metastatic progression by influencing cytoskeletal dynamics." (PMID 40350979, 2025). "Together, these findings suggest that WFDC3 significantly influences the immune landscape in PAAD, potentially promoting immune evasion and tumor progression through modulation of specific immune cell populations." (PMID 40350979, 2025). "SLPI, WFDC2, WFIKKN2, and WFDC1 consistently showed low expression across tumor types, whereas WFDC5, WFDC3, and WFIKKN1 displayed heterogeneous expression profiles." (PMID 40350979, 2025). "Statistical analysis showed significant tumor-specific upregulation of WFDC1, WFDC2, WFDC3, SLPI, PI3, and ANOS1 (P < 0.0001), while WFIKKN1 was notably downregulated in neoplastic tissues (P < 0.0001)." (PMID 40350979, 2025). "Transcriptional profiling using TCGA datasets revealed elevated WFDC3 expression in PAAD tumor tissues compared to adjacent or normal pancreatic tissues." (PMID 40350979, 2025). "Moreover, there was clinical significance to WFDC3 in CRC, as CRC patients with high WFDC3 expression in tumor cells had favorable prognoses." (PMID 37443102, 2023).
WFDC3 also shares sentences with these, for which no sentence is quoted: prostate carcinoma (1 paper).